EPCAM (epithelial cell adhesion molecule)
Diseases named in the same sentence as EPCAM in open-access papers (continued):
Sharing a sentence is not in itself a finding about the gene and the disease.
hepatocellular carcinoma (continued). "Studies conducted with human hepatocellular carcinoma cell lines suggested that EpCAM expression distinguished cells with stem-like properties from cells that were more differentiated." (PMID 20046825, 2009). "It has also been reported that EpCAM was expressed by stem cells in colon cancers and hepatocellular carcinomas." (PMID 20046825, 2009). "In addition, other epithelial-derived malignancies including colorectal, pancreatic, and hepatocellular carcinomas also exhibit substantial frequencies of EpCAM-positive CTCs." (PMID 41459333, 2026). "Additionally, aptamer-coated EVs have shown effective targeting in cancers such as hepatocellular carcinoma (HCC) by binding to EpCAM." (PMID 40317075, 2025). "In hepatocellular carcinoma (HCC) cells expressing the liver CSC marker EpCAM, inhibition of mTOR complex 2 (mTORC2) or activation of mTORC1 leads to reduced EpCAM expression, thereby decreasing the tumorigenic potential of CSCs and increasing sensitivity to the antiproliferative effects of 5-FU." (PMID 40438606, 2025). "In addition, the JUNB expression in EpCAM-positive hepatoma cells was increased by paracrine stimulation with fibroblast-derived TGFb1." (PMID 40253402, 2025). "The rate of EpCAM positivity was especially lower than of CKpan staining in hepatocellular carcinomas, mesotheliomas, squamous cell carcinomas, and in very poorly differentiated tumors such as anaplastic cancers of the thyroid or sarcomatoid urothelial carcinomas." (PMID 38786342, 2024). "Furthermore, EpCAM and β-catenin were reported to be expressed in spheroids derived from hepatocellular carcinoma (HCC) cells." (PMID 37303738, 2023). "Furthermore, study in hepatocellular carcinoma (HCC) suggested that tumor growth and invasion were associated with EpCAM-positive cells, which was one of the components of targeting Wnt/beta-catenin signaling pathway." (PMID 37875600, 2023). "NuRD complex interacts with SALL4 to regulate stemness of EpCAM-positive hepatocellular carcinoma." (PMID 37880213, 2023). "In addition, matrine-derived compounds can inhibit the development of hepatocellular carcinoma by reducing the expression of Bcl-2, inducing cell cycle arrest, reducing the number of EpCAM and CD133 cells, and inhibiting the expression of CSC markers." (PMID 36686745, 2022). "By virtue of expressing EpCAM, CTCs are predictive of poor outcome and are preferentially involved in the formation of lung metastasis in breast cancer patients as well as postsurgical recurrence in hepatocellular carcinoma (HCC) patients." (PMID 34455700, 2021). "Moreover, study in hepatocellular carcinoma reported that EpCAM expression in this cancer type is regulated by the WNT signalling pathway via its downstream transcriptional effectors, TCF and Lef1." (PMID 32046162, 2020). "For example, CHD4 has been shown to regulate EpCAM+ liver cancer stem cells and chemoresistance in human hepatocellular carcinoma, supporting the hypothesis that the NuRD complex regulates oncogenesis via multiple mechanisms." (PMID 32070428, 2020). "Next, we found that the proportion of EpCAM in miR-28-5p knockdown hepatoma cells was upregulated." (PMID 31885628, 2019). "Therefore, in this study, we prepared EpCAM+ HepG2 lysates and EpCAM peptides from hepatoma stem-like cells for use in antigen-loaded DC-based vaccines." (PMID 29298343, 2018). "EpCAM positive expression has been found in 15.9% to 48.7% of all hepatocellular carcinomas." (PMID 30112355, 2018). "In order to determine whether YB-1 affected the population of HCC initiating cells, we investigated side-population and EpCAM+ hepatoma cells by flow cytometry." (PMID 27911878, 2017). "In addition, clone formation and sphere formation of hepatoma cells were accelerated and cancer stem markers including EPCAM and NANOG were up-regulated." (PMID 28646927, 2017). "Recent studies showed that EpCAM expression may be regulated by the Wnt/β-catenin signaling pathway in hepatoma cells." (PMID 28851352, 2017).
hepatocellular carcinoma (continued). "Recent reports have identified CTSCs, which have CSC-like potential and enhanced metastatic capacity in various solid tumors, such as breast, colon, and hepatocellular carcinoma, using a combination of EpCAM and CSC markers in the each tumor (e.g., CD44 or CD133)." (PMID 26897248, 2016). "EpCAM is up-regulated in the majority of human epithelial carcinomas, including colorectal, breast, prostate, lung, cervical epithelium, colon, head and neck, and hepatic carcinomas." (PMID 26984381, 2016). "EpCAM is used as a cancer stem cell marker, and as an early biomarker of hepatocellular carcinoma." (PMID 26984381, 2016). "Similarly, in the case of hepatocellular carcinoma, EpCAM+ α-fetoprotein+ cells show characteristics of CSCs/CPCs." (PMID 23213278, 2012). "The results were further validated by RT-PCR, western blot, flow cytometry or immunofluorescent staining which revealed that prominin-1, annexin A1, annexin A3, transgelin, creatine kinase B, vimentin, and EpCAM were indeed highly expressed in the CD133-positive hepatoma cells." (PMID 23170877, 2012). "In addition, selective knockdown of EpCAM in hepatocellular carcinoma stem cells attenuated their ability to form tumors in immunocompromised mice and, even more strikingly, to metastasize." (PMID 20046825, 2009). "Circulating tumor cell (CTC) detection in hepatocellular carcinoma (HCC) is limited not only by the rarity of CTCs but also by a heavy reliance on cell surface markers such as EpCAM, which are variably expressed or lost during tumor progression." (PMID 41203725, 2025). "miR-2117, functioning as a tumor suppressor, inhibits the self-renewal of CSCs by directly repressing the transcription factor SOX2 in sorted EpCAM+ or CD24+ primary hepatocellular carcinoma (HCC) cells." (PMID 40710326, 2025). "Transplantation of EpCAM+CD45− cells isolated from patients with hepatocellular carcinoma (HCC) into NOD/SCID mice triggered tumor formation, while EpCAM−CD45− cells did not have the same effect." (PMID 37853413, 2023). "Previously, we demonstrated that the development of hepatocellular carcinoma (HCC) is dictated by a subset of epithelial cell adhesion molecule-positive (EpCAM+) liver CSCs with the activation of Wnt signaling." (PMID 38003473, 2023). "As the melanoma antigen gene (MAGE) family number, MAGE-A9 exhibits a higher level of expression in EpCAM+ HCC cells, contributing to the stemness of hepatocellular carcinoma." (PMID 36910604, 2023). "In EpCAM+ hepatocellular carcinoma (HCC), as well as advanced cirrhosis liver tissues, autocrine Wnt signaling was activated, as evidenced by elevated expression of Wnt3, β-catenin, c-Myc and CCND1." (PMID 36369033, 2022). "Up-regulation of Sema3A expression promoted tumor growth and tumor progression in a hepatocellular carcinoma (HCC) mouse model by enhancement of the expression of CapG, galectin-3, enolase 2 and Epithelial cell adhesion molecule (EpCAM)." (PMID 30696103, 2019). "Therefore, this study investigated the functional consequences of enhanced expression of STIM1 and Orai1 in a tumor-initiating subpopulation of Huh-7 hepatocellular carcinoma (HCC) cells that express epithelial cell adhesion molecule (EpCAM) and Prominin 1 (CD133)." (PMID 31366337, 2019). "Previous work has demonstrated that Pimozide inhibited cell growth of Hepatocellular carcinoma (HCC) cells by disrupting the Wnt/β-catenin signaling pathway and reducing epithelial cell adhesion molecule (EpCAM) expression." (PMID 30405882, 2018). "In this study, we evaluated WM130, a novel derivative of matrine, for its effect on CSCs using human hepatocellular carcinoma (HCC) cell lines, their sphere cells, and sorted EpCAM+ cells." (PMID 27783993, 2016). "The epithelial cell adhesion molecule (EPCAM) is involved in the tumorigenesis and progression of many malignancies, including hepatocellular carcinoma (HCC)." (PMID 24718422, 2014).
hepatocellular carcinoma (continued). "The RNA contained Epithelial-cell adhesion-molecule (EpCAM) aptamers for targeted delivery and siRNA sequences for EpCAM gene silencing, and CD could load the first-line drug sorafenib for the targeted therapy of hepatocellular carcinoma through its hydrophobic cavity." (PMID 39204399, 2024). "In hepatocellular carcinomas, 15.4% were positive for EpCAM alone, 15.4% were positive for TROP2 alone, and only 2.6% for both EpCAM and TROP2." (PMID 38786342, 2024). "Epithelial cell adhesion molecule is an integral membrane glycoprotein and is appraised as a prevailing marker for CSCs in numerous types of cancer-like prostate, breast, and hepatocellular carcinoma (HCC)." (PMID 39312080, 2024). "Further, the HMGCR-induced expression of EpCAM and CD133 on the surface of hepatoma cells was also identified by flow cytometry." (PMID 39022130, 2024). "Doxorubicin increased the expression of stemness-related genes, such as epithelial cell adhesion molecule (EpCAM), cytoskeletal 19 (CK19), annexin A3 (ANXA3), and the multidrug-resistance-related gene ABCG2 in hepatocellular carcinoma cells (HCCs)." (PMID 36834846, 2023). "EpCAM-specific CAR-T cellsEpCAM positive prostate, colon, oesophageal, pancreatic, hepatic carcinomas." (PMID 35158771, 2022). "TGF-β also produces the EpCAM+ CSC-like cells through induction of epithelial to mesenchymal transition (EMT) program and these cells, in turn, promote hepatocellular carcinoma (HCC) invasion and metastasis." (PMID 35395787, 2022). "In hepatocellular carcinoma, KLF4 directly activated EpCAM, increased the number of EpCAM+/CD133+ liver cancer stem cells in vitro, and amplified the tumorigenesis in vivo." (PMID 34680284, 2021). "Additionally, stemness genes, such as Nanog, Sox2, and Oct4, were expressed in EpCAM-positive HCC cells and TSC2-AKT signaling activated upon Sorafenib treatment, further exacerbating hepatocellular carcinoma progression." (PMID 32466488, 2020). "Epithelial cell adhesion molecule [EpCAM] is a surface marker of cancer stem cells that can maintain the capacity for malignant proliferation, invasion, metastasis, and tumor recurrence; hence its detection among hepatocellular carcinoma [HCC] patients may be an important prognostic factor." (PMID 32212818, 2020). "Furthermore, miR-150, miR-155, miR-181, and miR-223 expression is increased in EpCAM+ hepatocellular carcinoma (HCC)." (PMID 31921628, 2019). "Nonetheless, the prognostic values of the peritumoral expression of EpCAM and CD13 remain to be elucidated in hepatocellular carcinoma (HCC) patients." (PMID 28572700, 2017). "WM130 also suppressed the proliferation of doxorubicin-resistant hepatoma cells, and markedly reduced the cells with CSC biomarker EpCAM." (PMID 27783993, 2016). "Recently, EpCAM and CD133 were identified as direct transcriptional targets of the Wnt/β-catenin signaling in hepatocellular carcinoma (HCC)." (PMID 31656694, 2016). "Previous studies have reported that in the hepatoma cell k\line CD133 and EpCAM expression cells differentiated into non-CD133 and non-EpCAM expressing cells as the days of culture increased." (PMID 26457068, 2015). "Indeed, Yamashita and colleagues have shown that EpCAM+/α-fetoprotein tumor cells display hepatic cancer stem-cell traits, including the abilities to self-renew and differentiate and to be able to initiate highly invasive hepatocellular carcinoma in NOD/SCID mice." (PMID 25477371, 2015). "In hepatocellular carcinoma (HCC), cell membrane proteins such as CD133, CD13, CD90, EpCAM and CD44 have been widely applied to isolate different types of hepatic cancer stem cells (hCSCs)." (PMID 26571119, 2015). "Consistent with previous studies, we have found that CD133 (+) hepatocellular cancer cells highly express stemness genes (CD44, EpCAM, Oct4 and KLF4) and exhibit increased sphere formation capacity compared to the CD133 (−) cells." (PMID 26506419, 2015).
hepatocellular carcinoma (continued). "The three types of EpCAM-positive hepatoma cells that overexpressed SOX4 showed no increase in CD90 expression." (PMID 40253402, 2025). "Key markers, such as PTPRC, CD3E, CD4, CD79A, and CD3G in immune cells, EPCAM and KRT19 in epithelial cells, and MME and PECAM1 in stromal cells, were identified, providing crucial insights into hepatocellular carcinoma progression and immune response mechanisms." (PMID 39388011, 2024). "A comparison of EpCAM and CKpan staining identified a high concordance but EpCAM was higher in testicular seminomas and neuroendocrine neoplasms and CKpan in hepatocellular carcinomas, mesotheliomas, and poorly differentiated non-neuroendocrine tumors." (PMID 38786342, 2024). "Hepatocellular carcinomas can be distinguished from metastatic adenocarcinomas or cholangiocarcinomas by their general lack of EpCAM expression." (PMID 37627911, 2023). "The authors demonstrated that casticin reduced stemness characteristics in two lines of hepatocellular carcinoma (HCC), MHCC97H and SK-Hep-1, by reducing the CD44+ cell population, the CD44 protein levels, and the expression of stemness biomarkers EpCAM, Bmi, Nanog, and Oct4 mRNAs." (PMID 37304067, 2023). "Thus, we analyzed the expression of epithelial surface protein (EpCAM) and cytoskeleton protein cytokeratin 19 (CK19), both of which are enriched in liver carcinomas with stem cell features, in the rosette cells." (PMID 35879421, 2022). "Matrine could significantly inhibit the activation of Akt in hepatoma cell lines HepG2 and Huh7, inhibit the expression of stem cell genes such as CD90, CD133 and EpCAM, and then inhibit the proliferation and metastasis of hepatoma cells." (PMID 35433636, 2022). "Notably, expression of this miRNA has also been reduced in CD133 or EpCAM-positive hepatic CSCs and in CSC-enriched spheres in hepatoma." (PMID 34368145, 2021). "In liver neoplasia, almost all cholangiocarcinomas express EpCAM, whereas the majority of hepatocellular carcinomas are EpCAM negative, suggesting that malignant proliferation of hepatocellular carcinoma cells is not related to expression of EpCAM32." (PMID 31068623, 2019). "At variance with hepatocellular carcinoma (HCC), in which the features of cells with different CD133/EpCAM phenotypes were subjected to both in vitro and in vivo characterization, no information is available on TNBC derived cells showing variable surface levels of the two antigens." (PMID 28870198, 2017). "In hepatocellular carcinoma (HCC), CD133 and EpCAM have been identified as CSC markers." (PMID 24312415, 2013). "For example, micelles consisting of αvβ3 integrin-targeted cyclic RGD-PEG-DSPE or epithelial cell adhesion molecule (EpCAM)-targeted Epi-1 peptide-PEG-DSPE were synthesized and used to prepare targeted LNPs for treating metastatic lung tumors or Hep-3B hepatocellular cancer, respectively." (PMID 38516300, 2023). "Interestingly, the EpCAM-based IsoFlux System, with only slightly higher blood volume suitable for testing (up to 10 mL), presented a very high CTC recovery rate in prostate and hepatocellular cancer patients." (PMID 31185699, 2019). "In human hepatocellular carcinoma (HCC), a number of TIC markers have been identified including CD133, EpCAM, and CD90, whose functions were well-characterized using both cell lines and primary tumor specimens." (PMID 24713374, 2014). "In this study, we examined the effects of BCAA on hepatocellular carcinoma (HCC) cells expressing a hepatic CSC marker, EpCAM." (PMID 24312415, 2013). "They found that BMP9-ID1 signaling promotes epithelial cell adhesion molecule(EpCAM)-positive cancer stem cells by activating Wnt/β-catenin signaling, which indicates that BMP9 and ID1 may be involved in the occurrence and development of hepatocellular carcinoma." (PMID 39619441, 2024). "These tumors were diagnosed as hepatocellular carcinoma with the expression of GPC3 and EPCAM, but lacking MYC overexpression." (PMID 39529166, 2024).
hepatocellular carcinoma (continued). "OATP1B3, a transporter of bile acids, was found to be highly expressed in green hepatoma, and HCCs with high expression of OATP1B3 were negative for cancer stem cell markers, including cytokeratin-19 (CK19) and EpCAM." (PMID 35053606, 2022). "In hepatocellular carcinoma (HCC), EpCAM is considered a CSC marker and EpCAM positive HCC cell lines were shown to have increased proliferative properties compared to EpCAM negative cells." (PMID 34209658, 2021). "Cells that meet the four indexes of CD133+, CD44+, CD24+, and EpCAM+ are defined as human liver cancer stem cells (hLCSCs), and cells that satisfy the four indexes of CD133-, CD44-, CD24-, and EpCAM are defined as non-hepatoma stem cells (non-hLCSCs)." (PMID 31900225, 2020). "In our previous studies, two poorly differentiated hepatoma subpopulations, Huh‐7‐trans and Huh‐7‐DN with aberrant Hh activation, were isolated from their parental Huh‐7 cells by fluorescence‐activated cell sorting (FACS) with a negative CD133/EpCAM surface marker profile." (PMID 32108992, 2020). "Additionally, from a hepatocellular carcinoma patient, we established a novel HCC cell line, named HCC1, that exhibits a strong EpCAM but no CD90 expression." (PMID 35454789, 2022).